CTNNA1P1 (catenin alpha 1 pseudogene 1)
Synonyms: formerly CTNNAP1
Gene: Processed pseudogene on chromosome 5 (115,389,643 to 115,392,370, reverse strand). Ensembl gene ENSG00000249026.
Diseases named in the same sentence as CTNNA1P1 in open-access papers:
CTNNA1P1 is named in the same sentence as 4 diseases in open-access papers, as found by Europe PMC text mining. Sharing a sentence is not in itself a finding about the gene and the disease. The quoted sentences say what the papers report.
colorectal cancer (4 papers, 2016 to 2022). A primary or metastatic malignant neoplasm that affects the colon or rectum. "A decreased expression level of CTNNA1P1 has been associated with the pathogenesis of colorectal cancer." (PMID 33478113, 2021).
CTNNA1P1 also shares sentences with these, for which no sentence is quoted: cancer (2 papers); tumor (2); lung adenocarcinoma (1).